KHNYN (KH and NYN domain containing)
Synonyms: KIAA0323
Tractability: PROTAC: ubiquitination databases record sites on it; its protein half-life has been measured.
Gene: Protein-coding gene on chromosome 14 (24,423,052 to 24,441,843, forward strand). Ensembl gene ENSG00000100441.
Subcellular location (Human Protein Atlas): Nucleoplasm; Cytosol; Nuclear membrane
Gene Ontology:
Molecular function: protein binding; mRNA binding; RNA endonuclease activity; RNA binding
Biological process: 3'-UTR-mediated mRNA destabilization
Cellular component: cytoplasmic ribonucleoprotein granule; nucleus
Genetic constraint (gnomAD): Loss-of-function variants: 42 observed, 63.69 expected, observed/expected ratio (o/e) 0.66, 90% interval 0.51 to 0.85. The upper end of that interval is the gene's LOEUF score, 0.85, which puts it in group 3 of 6, group 1 being the genes least tolerant of losing a copy. Missense variants: 829 observed, 897.48 expected, observed/expected ratio (o/e) 0.92, 90% interval 0.87 to 0.98. Synonymous variants: 347 observed, 355.29 expected, observed/expected ratio (o/e) 0.98, 90% interval 0.89 to 1.07.
Homologues: Orthologues: chimpanzee KHNYN (99% identical), macaque KHNYN (97% identical), dog KHNYN (83% identical), pig KHNYN (83% identical), rabbit KHNYN (80% identical), rat Khnyn (80% identical), mouse Khnyn (79% identical), guinea pig KHNYN (79% identical), Drosophila melanogaster Regnase-1 (17% identical), Caenorhabditis elegans rege-1 (15% identical), Drosophila melanogaster CG42360 (12% identical), Caenorhabditis elegans Y24D9B.1 (9% identical), and 2 more. Paralogues in human: NYNRIN (42% identical), N4BP1 (32% identical), ZC3H12C (19% identical), ZC3H12A (18% identical), ZC3H12B (17% identical), ZC3H12D (16% identical).
Diseases named in the same sentence as KHNYN in open-access papers:
KHNYN is named in the same sentence as 8 diseases in open-access papers, as found by Europe PMC text mining. Sharing a sentence is not in itself a finding about the gene and the disease. The quoted sentences say what the papers report.
viral infection (3 papers, 2019 to 2025). "In this way, ZAP directed KHNYN endoribonuclease activity would be licensed through the release of Mn2+ only after viral infection preventing off-target RNA decay." (PMID 41404804, 2025). "Whether KHNYN is regulated by type I interferons or viral infection in a different way, such as post-translational modification, is not known." (PMID 31284899, 2019).
influenza (2 papers, 2025). An acute viral infection of the respiratory tract, occurring in isolated cases, in epidemics, or in pandemics; it is caused by serologically different strains of viruses (influenzaviruses) designated A, B, and C, has a 3-day incubation period, and usually lasts for 3 to 10 days. "Future work will benefit from examining ZAP, KHNYN, and TRIM25 susceptibility of many influenza strains derived from humans, wild birds, agricultural poultry, and domestic mammals as well as emerging mammalian H5N1 IAV isolates." (PMID 39763980, 2025).
lung adenocarcinoma (2 papers, 2025). A carcinoma that arises from the lung and is characterized by the presence of malignant glandular epithelial cells. "Therefore, we generated multiple human lung adenocarcinoma A549 clonal cell lines depleted for ZAP, KHNYN, or both by CRISPR/Cas9 genome editing as well as a vector control (Vector) and a negative control guide targeting E. coli LacZ beta-galactosidase (LacZ) clonal cell lines." (PMID 39763980, 2025). "Therefore, we generated multiple human lung adenocarcinoma A549 clonal cell lines depleted for ZAP, KHNYN, or both by CRISPR/Cas9 genome editing as well as a vector control (Vector) and a negative control guide targeting Escherichia coli LacZ beta-galactosidase (LacZ) clonal cell lines." (PMID 41150682, 2025).
tumor (2 papers, 2009 to 2021). "Some genes, like KHNYN, HBQ1, SCD5 and FLVCR2, may play roles in tumorigenesis, metabolism or tumor therapy." (PMID 34568059, 2021).
KHNYN also shares sentences with these, for which no sentence is quoted: glioma (2 papers); asthma (1); breast tumors (1); cancer (1).